UBE3A (ubiquitin protein ligase E3A)
Diseases named in the same sentence as UBE3A in open-access papers (continued):
Sharing a sentence is not in itself a finding about the gene and the disease.
esophageal cancer (2 papers, 2021 to 2023). A primary or metastatic malignant neoplasm involving the esophagus. "Because UBE3A possesses an E3 ligase function, and the protein level of ZNF185 was negatively associated with UBE3A, we hypothesized that UBE3A might be involved in promoting the degradation of ZNF185 in esophageal cancer." (PMID 34421347, 2021). "We further showed that UBE3A degraded ZNF185 to modulate the growth of esophageal cancer cells and activate the NOTCH signaling pathway." (PMID 34421347, 2021). "We first achieved stable UBE3A knockdown by lentivirus-based short hairpin RNA (shRNA), using the Eca-109 and TE-1 esophageal cancer cell lines." (PMID 34421347, 2021). "Collectively, our results suggest that UBE3A is aberrantly upregulated in specimens from patients with esophageal cancer." (PMID 34421347, 2021). "Together, these results suggested that ZNF185 is a degradation target of UBE3A in esophageal cancer cells." (PMID 34421347, 2021). "Next, we used subcutaneously injected xenografts of esophageal cancer cells in nude mice to study the tumor-growth related effects of UBE3A in vivo." (PMID 34421347, 2021). "Taken together, our data indicate that the UBE3A/ZNF185/NOTCH axis is important in the progression of esophageal cancer." (PMID 34421347, 2021). "In this study, we explored the mechanism underlying post-transcriptional regulation of ZNF185; we found that ZNF185 underwent ubiquitin-dependent proteasome degradation in the presence of UBE3A in esophageal cancer cells." (PMID 34421347, 2021). "We found that UBE3A was up-regulated in the esophageal cancer, which contributed to the progression of esophageal cancer." (PMID 34421347, 2021). "The UBE3A expression level was elevated in esophageal cancer tissues, compared with normal esophageal tissues." (PMID 34421347, 2021). "Taken together, our data suggested that UBE3A activates the NOTCH pathway via ZNF185 in esophageal cancer cells." (PMID 34421347, 2021). "In this study, we systematically explore the cancer related role of UBE3A in esophageal cancer." (PMID 34421347, 2021). "This overexpressed UBE3A promoted proliferation and invasion by esophageal cancer cells in vitro." (PMID 34421347, 2021). "Thus, our results indicated that UBE3A was responsible for the cellular progression of esophageal cancer." (PMID 34421347, 2021). "Similarly, UBE3A protein and mRNA levels were higher in esophageal cancer tissues than in adjacent normal tissues from resected esophageal cancer specimens in our hospital through Western blot analysis and RT-qPCR analysis respectively." (PMID 34421347, 2021). "We systematically investigated the role of UBE3A in esophageal cancer." (PMID 34421347, 2021). "In this study, we demonstrated that UBE3A was upregulated in esophageal cancer." (PMID 34421347, 2021). "Overall, these data demonstrated that UBE3A is aberrantly upregulated in esophageal cancer." (PMID 34421347, 2021). "This upregulated UBE3A participates in the cellular progression of esophageal cancer." (PMID 34421347, 2021). "Because UBE3A promoted the progression of esophageal cancer cells, we investigated whether ZNF185 influenced the UBE3A-induced tumor growth in esophageal cancer cells." (PMID 34421347, 2021). "Furthermore, we found that UBE3A promotes ZNF185 degradation to activate the NOTCH signaling pathway in esophageal cancer cells." (PMID 34421347, 2021). "Therefore, we concluded that UBE3A interacted with ZNF185 and was negatively associated with the protein level of ZNF185 in esophageal cancer." (PMID 34421347, 2021). "The deregulation of UBE3A reportedly promotes or suppresses various types of malignant tumors 17.However, the role of UBE3A in esophageal cancer remains unclear." (PMID 34421347, 2021). "Moreover, the mRNA and protein expression levels of UBE3A were elevated in esophageal cancer cell lines (including Eca-109, TE-1 and TE-3), compared with normal esophageal epithelial cells, such as Het-1A." (PMID 34421347, 2021).
esophageal cancer (continued). "Furthermore, UBE3A knockdown significantly inhibited esophageal cancer cell invasion." (PMID 34421347, 2021). "Thus, UBE3A acted as an oncogenic protein in esophageal cancer." (PMID 34421347, 2021). "Moreover, we found that UBE3A degraded ZNF185 in esophageal cancer." (PMID 34421347, 2021). "To test this hypothesis, we performed UBE3A knockdown in three esophageal cancer cell lines." (PMID 34421347, 2021). "The role of UBE3A and ZNF185 in esophageal cancer growth was assessed by MTS assays, colony formation assays, and experiments in mouse xenograft models." (PMID 34421347, 2021). "However, the cancer-related role of UBE3A in esophageal cancer remains unclear." (PMID 34421347, 2021). "Thus, UBE3A might act as an oncogenic protein in esophageal cancer cells." (PMID 34421347, 2021). "Co-immunoprecipitation analyses demonstrated that UBE3A bound to ZNF185 in a reciprocal manner in both Eca-109 and TE-1 esophageal cancer cells." (PMID 34421347, 2021). "Therefore, UBE3A might be an ideal therapeutic candidate for esophageal cancer." (PMID 34421347, 2021). "Subsequently, we checked the protein levels of UBE3A in tissue microarrays (TMAs) (Cat No. D880101, Bioaitech, CN) from patients with esophageal cancer (n = 85) by immunohistochemistry (IHC)." (PMID 34421347, 2021). "In contrast, UBE3A overexpression led to reduced protein expression of ZNF185, but did not impact is mRNA expression, in all three esophageal cancer cell lines." (PMID 34421347, 2021). "UBE3A knockdown led to enhanced protein expression of ZNF185, but did not impact its mRNA expression, in all three esophageal cancer cell lines." (PMID 34421347, 2021).
Hepatic steatosis (2 papers, 2023). Steatosis is a term used to denote lipid accumulation within hepatocytes. "UBE3A regulation of ACAT1 proteinstability also bears physiological significance, as overexpressingUBE3A in the mouse liver downregulates ACAT1 protein contents, increasescirculating ketone levels, and promotes hepatic steatosis." (PMID 36920305, 2023).
renal cell carcinoma (2 papers, 2021 to 2022). "RRM2 overexpression plays a key role in sunitinib resistance in patients with renal cell carcinoma and that RRM2 competes with UBE3A to prevent ANXA1 degradation." (PMID 34319001, 2021).
albinism (1 paper, 2008). A congenital disorder characterized by partial or complete absence of melanin pigment in the eyes, hair, or skin. "These genomic probes except P2 were generated by PCR amplification from genomic DNAs and are located close to the CpG island of CYFIP1 (P1), the 3'-end of the UBE3A gene (P3), the CpG island of ATP10A (P4), and the CpG island of the P locus for albinism." (PMID 18226259, 2008).
Aleutian disease (1 paper, 2024). "From this, we identified several candidate genes contributing to the growth and feed efficiency (ARID1B, APPL1, TOX, and GPC5), reproduction (GRM1, RNASE10, WNT3, WNT3A, and WNT9B), pelt quality (MYO10, and LIMS1), and Aleutian disease tests (IFNGR2, APEX1, UBE3A, and STX11)." (PMID 38167844, 2024).
cerebral palsy (1 paper, 2024). A group of disorders affecting the development of movement and posture, often accompanied by disturbances of sensation, perception, cognition, and behavior. "One-fifth (20%) of the misdiagnoses were ones of cerebral palsy, which was most frequently diagnosed in the group of patients with the UBE3A mutation—37.5%." (PMID 39174987, 2024). "One-fifth of the patients (20%) had previously been diagnosed with cerebral palsy (CP), mostly among the UBE3A mutation group, which may be due to the mildest clinical presentation of patients with this genetic background." (PMID 39174987, 2024).
Charcot-Marie-Tooth disease (1 paper, 2011). An inherited degenerative disorder involving the peripheral nerves. "Only eight of the events (all hotspot sites) associated with genomic disorders, including 22q11.2 deletion (TBX1, DiGeorge syndrome), 17p12 duplication (PMP22, Charcot-Marie-Tooth disease), and 15q11.2q13.1 duplication (UBE3A and SNRPN)." (PMID 22102821, 2011).
colorectal cancer (1 paper, 2021). A primary or metastatic malignant neoplasm that affects the colon or rectum. "Interestingly, NDRG2 in colorectal cancer could affect the complex components of ubiquitin-protein ligase E3A (UBE3A) and estrogen receptor beta (ERβ), reducing the ubiquitin-mediated proteasome degradation of ERβ, demonstrating that NDRG2 could bind to UBE3A to hinder the binding of UBE3A to ERβ." (PMID 34885221, 2021).
COVID-19 (1 paper, 2025). A disease caused by infection with severe acute respiratory syndrome coronavirus 2. "Additionally, in critical and severe COVID-19 cases, gradual upregulation of UBE3A expression was detected, which previously has been linked to favorable COVID-19 outcomes." (PMID 41141600, 2025). "Moreover, one of the key COVID-19-induced compensatory gene pathways include the enhanced expression of UBE3A which drives a ubiquitin-modulated host response to COVID-19 and is positively associated with reduced disease severity." (PMID 41141600, 2025). "Interestingly, UBE3A which emerged as the most significant gene from the ‘yellow’ module in the WGCNA analysis step was found to be upregulated at 12 weeks in critically and severely-ill COVID-19 patients who had recovered, but it was less expressed in the former group than the latter." (PMID 41141600, 2025).
encephalopathies (1 paper, 2025). "The genes NDN, SNRPN, and UBE3A are known for their association with Prader–Willi syndrome; GABRB and GABRA5 are associated with encephalopathies; OCA2 and HERC2 are linked to skin pigmentation." (PMID 40149731, 2025).
invasive breast carcinoma (1 paper, 2021). A carcinoma that infiltrates the breast parenchyma. "In contrast, UBE3A binds with ER-α to promote ER-α proteasome degradation; reduced expression of UBE3A has been associated with poor prognosis in human invasive breast cancers." (PMID 34421347, 2021).
Liddle syndrome (1 paper, 2011). A rare genetic form of low-renin hypertension characterized by hypertension associated with decreased plasma levels of potassium and aldosterone. "HECT-E3s have been linked to AS (UBE3A), Liddle's syndrome (Nedd4-I), tuberous sclerosis complex (HERCI) and cancer (Smurf2, UBE3A and EDD), suggesting the functional spectrum of these proteins." (PMID 21633703, 2011).
melanoma (1 paper, 2025). A malignant, usually aggressive tumor composed of atypical, neoplastic melanocytes. "SLCA11.AS1 inhibits the degradation of CTCF by preventing its ubiquitination by Ubiquitin Protein Ligase E3A (UBE3A), thus promoting melanoma progression." (PMID 40076754, 2025).
memory impairment (1 paper, 2020). "Learning and memory impairments have been observed in some but not all studies of Ube3a mutant mouse models depending on the background strain and age at time of testing." (PMID 32066685, 2020).
Merkel cell carcinoma (1 paper, 2023). "Here, we report that PIEZO2 activity is reduced in Ube3a deficient male and female mouse sensory neurons, a human Merkel cell carcinoma cell line and female human iPSC-derived sensory neurons with UBE3A knock-down, and de-identified stem cell-derived neurons from individuals with AS." (PMID 36859399, 2023).
microdeletion syndrome (1 paper, 2024). "Of CNV syndromes, Chromosome 15q11-q13 microdeletion syndrome (UBE3A involved) (3/20, 15.0%) was the most frequent, followed by Chromosome 1q21.1 microdeletion syndrome (GJA5 involved) (2/20, 10.0%)." (PMID 38764027, 2024).
Miscarriage (1 paper, 2024). A pregnancy that ends at a stage in which the fetus is incapable of surviving on its own, defined as the spontaneous loss of a fetus before the 22th week of pregnancy.
nasopharyngeal carcinoma (1 paper, 2024). A carcinoma arising from the nasopharyngeal epithelium.
osteoporosis (1 paper, 2022). A condition of reduced bone mass, with decreased cortical thickness and a decrease in the number and size of the trabeculae of cancellous bone (but normal chemical composition), resulting in increased fracture incidence. "Our findings demonstrate that Calcrl, Marco, and Ube3a are novel determinants of osteoclastogenesis, especially with respect to cell fusion, and highlight potential targets for osteoporosis therapy." (PMID 35742859, 2022).
overnutrition (1 paper, 2023). An imbalanced nutritional status resulting from excessive intake of nutrients. "Moreover, Ube3a suppressed overnutrition-induced NAFLD by targeting and degrading MLL4." (PMID 36839306, 2023).
Pick disease (1 paper, 2025). A rare neurodegenerative disorder leading to dementia. "In our immunofluorescence staining of UBE3A, we noted a statistically significant decrease in UBE3A levels in human PFC, specifically in Pick’s disease brains." (PMID 41223260, 2025).
psychosis (1 paper, 2022). "Overexpression of UBE3A can disrupt these systems, which disturbs the excitatory–inhibitory balance in the brain, possibly leading to psychosis." (PMID 35887798, 2022). "A likely explanation for the increased prevalence of psychosis in adults with mUPD is overexpression of the (in the brain) paternally imprinted gene UBE3A." (PMID 35887798, 2022). "Overexpression of UBE3A may be the second hit, ultimately leading to psychosis in adults with an mUPD." (PMID 35887798, 2022). "The hypothesis that overexpression of UBE3A can result in psychosis is supported by studies about patients with a 15q11-q13 duplication." (PMID 35887798, 2022).
spinocerebellar ataxia type 1 (1 paper, 2025). Spinocerebellar ataxia type 1 (SCA1) is a subtype of type I autosomal dominant cerebellar ataxia (ADCA type I) characterized by dysarthria, writing difficulties, limb ataxia, and commonly nystagmus and saccadic abnormalities. "Loss of UBE3A also exaggerates Purkinje cell loss in spinocerebellar ataxia type 1 (SCA1) mice." (PMID 40076922, 2025).
steatosis (1 paper, 2023). Increased lipid within the cytoplasm of cells. "Furthermore, wefound that the forced expression of UBE3A in the mouse liver promoteshepatic steatosis as manifested by increased lipid deposition in theliver and higher levels of liver cholesterol and serum ketones." (PMID 36920305, 2023).
neurodevelopmental disorder (102 papers, 2012 to 2026). A behavioral and cognitive disorder with onset during the developmental period that involves impaired or aberrant development of intellectual, motor, or social functions. "AS (MIM:105830) is a neurodevelopmental disorder primarily affecting the nervous system, most often caused by a de novo mutation in the maternal UBE3A gene on chromosome 15q11–q13." (PMID 41462762, 2025). "For instance, AS is caused by mutations in the UBE3A gene, which is implicated in neurodevelopmental disorders." (PMID 40076702, 2025). "Our observations document an emerging class of neurodevelopmental disorders caused by gain-of-function mutations in UBE3A." (PMID 40316779, 2025). "AS is a rare neurodevelopmental disorder caused by the loss of function of the maternally expressed UBE3A gene in the brain." (PMID 38580983, 2024). "Optimum levels of UBE3A are important for healthy brain development, as observed in neurodevelopmental disorders linked with various genetic aberrations like the deletions, mutations, and copy number variations (CNVs) of UBE3A." (PMID 38248358, 2023). "AS is a unique neurodevelopmental disorder caused by the functional loss of the ubiquitin‐protein ligase E6‐AP (E6‐associated Protein) encoded by the UBE3A gene (OMIM:#601623)." (PMID 35225435, 2022). "UBE3A gene dysregulation is associated with neurodevelopmental disorders, but predicting the function of UBE3A variants remains difficult." (PMID 34815418, 2021). "The UBE3A gene encodes the ubiquitin E3-ligase protein, UBE3A, which is implicated in severe neurodevelopmental disorders." (PMID 32532103, 2020). "Our findings reinforce the association of maternally derived UBE3A overexpression with neurodevelopmental disorders and support that a spectrum of clinical severity is present within families." (PMID 32117010, 2020). "This discrepancy is likely due to paternal imprinting of UBE3A in most neurons, a gene implicated in neurodevelopmental disorders that encodes a ubiquitin-protein ligase and regulates synaptic development." (PMID 31312421, 2019). "Despite this powerful association with neurodevelopmental disorders, there is still much to be learned about UBE3A, including its cellular and subcellular organization in the human brain." (PMID 30364390, 2018). "Because UBE3A is selectively imprinted in mature neurons, epigenetic regulation of UBE3A has been associated with several neurodevelopmental disorders." (PMID 27909399, 2016). "The Snrpn-Ube3a and Dlk1-Dio3 regions have also been associated with several neurodevelopmental disorders." (PMID 23580197, 2013). "Indeed, Angelman syndrome, a severe neurodevelopmental disorder, is caused by maternal UBE3A deficiency." (PMID 36594817, 2023). "Similarly, the cardinal features of AS are attributable to the loss of expression of maternally inherited genes, and UBE3A in particular, which causes a distinct AS neurodevelopmental disorder." (PMID 32384786, 2020). "Furthermore, ∼20% of the altered ncRNAs mapped to three imprinted regions (Snrpn-Ube3a, Dlk1-Dio3 and Sfmbt2) that showed differential methylation and have been previously implicated in neurodevelopmental disorders." (PMID 23580197, 2013). "The neurophysiological underpinnings of UBE3A-mediated neurodevelopmental disorders are an unexplored arena and very little information is available for review." (PMID 38248358, 2023). "Some of the proteins dysregulated in AS and/or interact with UBE3A have also been shown to be affected in other neurodevelopmental disorders, including ASDs." (PMID 38248358, 2023). "We now investigated possible functional links between TCF4, MEF2C, ZEB2, UBE3A and ATRX which are all implicated in clinically overlapping, severe human neurodevelopmental disorders." (PMID 31988313, 2020). "While the cellular roles of UBE3A are not fully understood, it is known to play a role in neurodevelopmental disorders in a dose-dependent manner." (PMID 32532103, 2020).